IDH1 (isocitrate dehydrogenase (NADP(+)) 1)
Diseases named in the same sentence as IDH1 in open-access papers (continued):
Sharing a sentence is not in itself a finding about the gene and the disease.
tumor (continued). "IDH1-mutated CCAs constitute a group of neoplasms of particular interest in the biliary tract cancer field, due to a particular behavior and therapeutic implications." (PMID 36335135, 2022). "In the study, IDH1/2 mutations were correlated with age, origin, histological grade, tumor diameter, relapse, and mortality, and multivariate analysis revealed a significant association between IDH1/2 mutations and poor overall survival." (PMID 35163019, 2022). "The high EZH2 expression group was significantly associated with older age group (p = 0.003), higher tumour grade (p < 0.001), and IDH1 R132H immunonegativity (p = 0.039)." (PMID 36292072, 2022). "Pathologically sub classifying the tumour into IDH1 mutation and chromosome 1p/19q co-deletion status can improve patients’ therapeutic options." (PMID 36120909, 2022). "In more than 80% of these tumors, point mutations in IDH type 1 (IDH1) lead to expression of the tumor-specific protein IDH1R132H." (PMID 35599302, 2022). "Integrated work-up of the first tumor manifestation showed an IDH1 R132H mutation with IDH2 wildtype and TERT C250T promoter mutation." (PMID 35018523, 2022). "Analysis of the recurrence revealed an analogous molecular profile: The tumor showed an IDH1 R132H mutation with IDH2 wildtype and TERT C250T promoter mutation." (PMID 35018523, 2022). "Of all patients, only three (2.5%) showed IDH1 mutation, whereas 111 patients (91.7%) had an IDH1 wildtype tumor." (PMID 35692808, 2022). "The isocitrate dehydrogenase 1 (IDH1) mutation is a key molecular feature of the World Health Organization (WHO) Central Nervous System (CNS) tumor classification." (PMID 35303961, 2022). "More importantly, IDH1 mutations also regulate anti-tumor immunity via decreasing PD-L1 expression and reducing immunosuppressive cell infiltration, indicating its potential possibility in GBM immunotherapy." (PMID 36389748, 2022). "Several studies have demonstrated that resection of the entire tumor correlates with a better prognosis in patients with mutated IDH1, compared with the wild type." (PMID 35806478, 2022). "A number of tumor entities harbor PHGDH overexpression or IDH1 mutations and the subsequent changes in cancer metabolism can be targeted." (PMID 35635656, 2022). "In this study, we confirmed the correlation between VASH1 and LGG tissue expression, WHO grade, IDH1 mutation, tumor mutation burden (TMB), immune cell infiltration, and prognosis by using TCGA, GTEx, CCLE, CGGA, UALCAN, GEPIA2, and Timer databases." (PMID 36504559, 2022). "The level of transketolase in the peritumoral zone of the tumor was significantly higher for the IDH1 mutation group (U-criterion of Mann–Whitney p = 0.05; Kolmogorov–Smirnov criterion p = 0.1)." (PMID 35625744, 2022). "More patients with mMGMT versus uMGMT tumor status had IDH1 mutation–positive tumors (n = 13 vs 5, p = 0.05)." (PMID 34510238, 2022). "The biological functions of IDH1 mutation (R132) would be comprehensively evaluated from the regulatory networks, tumor immune microenvironment and clinical relevance." (PMID 35488886, 2022). "The distribution of Habitat 7 was significantly higher (mean 33.3% vs. 18.8%, median 34.7% vs. 15.4% P = 0.05, independent sampled Mann-Whitney U test) in IDH-1 wild-type tumor compared to IDH-1 mutated." (PMID 35911979, 2022). "The discovery of the oncometabolite 2-hydroxyglutarate in isocitrate dehydrogenase 1–mutated (IDH1-mutated) tumor entities affirmed the role of metabolism in cancer." (PMID 34941573, 2022). "Among the six IDH1-mutant patients identified by tumor tissue NGS, BEAMing detected the corresponding IDH1 mutation in the plasma of three patients at a single timepoint in each case." (PMID 35740557, 2022).
tumor (continued). "The selective vulnerability of IDH1R132H cells to knockdown of NAMPT and NMRK1 indicated that these cells used both pathways to synthesize NAD+, making both enzymes possible targets for the selective treatment of IDH1 mutated tumor cells." (PMID 35628596, 2022). "In contrast, tumor purity was higher in tumors with 1p/19q codeletion, IDH1 mutation (R132) and/or MGMT promoter mutation." (PMID 35865015, 2022). "This IDH1 mutation leads to an intracytoplasmic accumulation of 2-hydroxyglutarate (2-HG) which alters overall tumor metabolism." (PMID 35303961, 2022). "A particular focus of our efforts was to identify mutations of relevance to patient outcome and identify recurrent driver mutations in those tumours that are wild type for IDH1 and IDH2 mutations (IDHwt)." (PMID 36042521, 2022). "In this study, we conducted Sanger sequencing of formalin-fixed paraffin-embedded (FFPE) diagnostic tumor samples using a target-panel to search for recurrent mutations involving the IDH-1/IDH-2, TET-2, DNMT3A and RhoA genes in 59 cases of nMTCL." (PMID 36536430, 2022). "Six patients had carmustine (BCNU) wafers (Gliadel, Eisai, for Arbor Pharmaceuticals) placed in the tumor cavity at their initial surgeries, and it happened that five of six were IDH1 mutated." (PMID 35864254, 2022). "By synthesizing 14 CRs-related signature, a nomogram was constructed based on risk score, age, tumor grade, and IDH1 mutation status to predict the probability of 1-, 3 -, 5, and 10-years overall survival rates." (PMID 36246611, 2022). "If this tumor cell clone had been homozygous, with two different IDH1-mutant alleles (R132H and R132C), both mutations would have been detected in tumor and plasma with a similar VAF." (PMID 35740557, 2022). "There was no obvious difference between high and low KIF18A groups in other clinical features, including patient age, gender, tumor lateralization, and IDH1 mutations." (PMID 35464837, 2022). "There was also a significant interaction between age and IDH1- frequency (adjusted p = 2.1 × 10−4) indicating an age-dependent effect on mRNA abundance: mutated IDH1 was associated with a greater mRNA decrease in tumours arising in younger patients." (PMID 35017538, 2022). "The baseline sPD-L1 levels were significantly associated with tumor grade, IDH-1 mutation status and Ki-67 expression;PFS and OS were significantly worse in patients with higher baseline levels of sPD-L1 (p = 0.027 and 0.008, respectively)." (PMID 35386715, 2022). "Tumours with IDH1 or IDH2 mutations or those that are IDHwt have significantly different genetic pathways and outcomes in relation to TERT mutation." (PMID 36042521, 2022). "Preclinically, olaparib delayed GB recurrence when combined with RT and sensitized IDH1-mutated tumor cells when combined with TMZ, leading to clinical trials in GB patients." (PMID 35406593, 2022). "Currently, preclinical studies represent the sole means of investigating the IDH1 mutation phenotype, independently of other mutations and tumor characteristics, in vivo." (PMID 35303961, 2022). "Due to its importance in prognosis, we have sequenced all tumours to assess IDH1 mutation status (IDH1R132H)." (PMID 35419292, 2022). "In the setting of other tumor associated Krebs-cycle mutations, such as IDH1/2, the build-up of oncometabolites has been shown to alter the immune microenvironment and potentially modulate response to immunotherapy." (PMID 36128328, 2022). "The median age at baseline was 59 years, 293 (59.8%) were male and 197 (40.2%) female, 51 (11% of 482 patients with available data) had IDH1 or IDH2 mutations detected in their tumours, and 234 (51% of 456) of patients had methylation of the MGMT promotor." (PMID 35804940, 2022). "Postoperative examination of tumor samples revealed the presence of IDH1 mutations in 24 of them, of which 16 showed luminosity." (PMID 35055109, 2022).
tumor (continued). "In that situation, if the IDH1/2 mutational status is different between the primary and the secondary tumors, the tumor origin is thought to be different between these two tumors." (PMID 35505351, 2022). "Mutations in the catalytic domains of IDH1 contribute to accumulation of 2-HG and modulation of anti-tumor immunity in GBM." (PMID 36389748, 2022). "In total, the tumor volume and weight were, respectively, decreased by erastin treatment as compared to that by DMSO treatment in IDH1 mutation group, indicating the simulative effects of erastin on inhibiting tumor growth." (PMID 35600114, 2022). "The involvement of these pathways in the regulatory network between IDH1 mutation-mediated tumor progression and ROS-induced ferroptosis, need validations of more molecular mechanism experiments." (PMID 35600114, 2022). "IDH wild-type tumours rarely exhibit TERT mutations and tend to be diagnosed in a younger population than those with tumours harbouring IDH1 and IDH2 mutations." (PMID 36042521, 2022). "LGGs are characterized by mutations in the IDH1 enzyme that decrease tumor aggressiveness by indirectly inhibiting the E2F transcription program, an important switch controlling homeostasis and tumorigenesis." (PMID 36471244, 2022). "Using NGS, seven patients harbored heterozygous IDH1 mutations in tumor tissue, including 5 patients with R132H, 1 patient with R132G, and 1 patient with R132C." (PMID 35740557, 2022). "In the multivariate analysis, age, tumor grade, IDH-1 mutations, and inflammation-nutrition score were found to be independently associated with the OS." (PMID 35495765, 2022). "In contrast, TERT mutations are rarer in IDH1-mutant tumours, yet they are associated with a less favourable outcome in this group." (PMID 36042521, 2022). "In the group with mutations of IDH1 genes, the content of transketolase is higher in the tissue of the peritumoral zone and tumor." (PMID 35625744, 2022). "It follows therefore that there is likely to be substantial overlap between the tumour cells harbouring an IDH1 and IDH2 mutation." (PMID 36286062, 2022). "The prognostic significance of the IDH1 R132H mutation is inconsistent and was associated with tumor WHO grade." (PMID 35888045, 2022). "Here, with the benefit of large sample numbers, we have been able to study tumours with IDH1 and IDH2 mutations independently and shown that they represent distinct genetic and clinical groups." (PMID 36042521, 2022). "Eleven patient tumors harbored a IDH1-R132H mutation, which allowed for a tumor cell-specific staining of tumor microtubes and their cell bodies." (PMID 35706996, 2022). "We performed Sanger sequencing analysis of the IDH1/2 gene in the primary tumor and found that the tumor had an IDH2 mutation." (PMID 35505351, 2022). "We identified distinct metabolites and metabolic pathways that were modulated by IDH1 mutation status, histology, and tumor therapies." (PMID 34941573, 2022). "We discovered comparison-specific metabolites and pathways modulated by IDH1 (IDH1 mutation status cohort) and tumor entity." (PMID 34941573, 2022). "The underlying mutational pathways of tumours with IDH1 or IDH2 mutations, or those that are IDHwt, differ significantly." (PMID 36042521, 2022). "A nomogram was constructed based on age, tumor grade, IDH-1 mutations, and inflammation-nutrition scores." (PMID 35495765, 2022). "The expression profile was compared with patient clinical data (age, survival time after the operation, tumor grade and location, mutation status of isocitrate dehydrogenase 1 (IDH1), and promoter methylation of O-6-methylguanine methyltransferase)." (PMID 36232448, 2022). "IDH1: Isocitrate dehydrogenase (IDH) 1 mutations are a defining characteristic of the histologically similar tumor, the astrocytoma IDH mutated WHO grade 4, which was previously characterized as a glioblastoma." (PMID 36011015, 2022).
tumor (continued). "We also use this prognostic signature and clinical parameters with P <0.01 to perform a joint effect survival analysis, these clinical parameters including age, grade, IDH1 mutation, radiation therapy and tumor location." (PMID 34164339, 2021). "Patients with unmethylated MGMT and IDH1 mutation, treated with different chemoradiotherapies, showed a late tumor recurrence." (PMID 34257620, 2021). "Other clinical features including age, gender, KPS, BMI, tumor grade, tumor size, extent of resection and IDH1 mutation status were similar between the two groups." (PMID 33596518, 2021). "Lower histological grades were associated with strong IRS class of IDH1, 46.3% of cases compared with 22.9% of grade 3 tumours." (PMID 33367952, 2021). "Most important of all, IDH1-mutated tumor showed an increased percentage of apoptotic cells after combining use ML309 and VC." (PMID 34425876, 2021). "At the genetic level, besides alterations in the β-catenin pathway, the tumor carried mutations in IDH1 and NRAS (codon 61) genes." (PMID 34205480, 2021). "Similar to observed in the CATNON dataset, a striking increase in DNA methylation levels was seen in non-R132H IDH1/2-mutated tumours compared to those harbouring a IDH1R132H mutation." (PMID 33740099, 2021). "Correspondingly higher expression of IDH1 was found to be significantly associated with smaller tumour size, lower tumour stage and histological grade suggesting that IDH1 expression is indicative of a positive prognostic outcome." (PMID 33367952, 2021). "The impact of the isocitrate dehydrogenase 1 (IDH1) mutation together with the methylation status of O6-methylguanine-DNA methyltransferase (MGMT) on RT-induced anti-tumor immunity against GBM is unclear." (PMID 34094969, 2021). "List of hospitals and corresponding total number of cases and number of IDH1/2 mutated and wild-type cases with respective tumor grades (II, III, and IV)." (PMID 33937440, 2021). "The 20–30% of central cartilaginous tumours without an IDH1/2 mutation highlights the need for additional prognostic biomarkers for patients whose tumours are WT for IDH1, IDH2 and GNAS mutations." (PMID 34528398, 2021). "For example, there were only 14 non-R132H IDH1/2-mutated 1p/19q codeleted tumours in the TCGA dataset, with only 1 event noted (in the IDH1R132H mutated tumours there were 14 events in 135 patients)." (PMID 33740099, 2021). "Hujber and co-workers found the IDH1-mutated tumor cells displayed remarkable sensitivity to mTORC1 inhibitor." (PMID 34425876, 2021). "Future meta‐analyses are needed to investigate the prognostic value of IDH1/2 mutations in these neoplasms." (PMID 34085407, 2021). "The mRNA expressions of PLAU and PLAUR varied remarkably among different ages, tumor histology, WHO grades and tumor types, IDH-1 mutation, and 1p19q status and other clinical characteristics." (PMID 35087738, 2021). "Mutations in ARID1A (p = 0.0205), ARID2 (p = 0.0207), BRAF (p = 0.023) SMARCA4 (p = 0.015), TERT (p = 0.0041), and IDH1 (p = 0.0041) were significantly exclusive to BM while the same variants remained undetected in the corresponding extracranial tumor tissues." (PMID 33578810, 2021). "Group differences in the ALPS index according to sex, tumor grade, and IDH1 mutation status were assessed using analysis of covariance with age adjustment." (PMID 34631582, 2021). "The Neural G0 eigengene was significantly associated with patient survival even with the inclusion of tumor grade and IDH1/2 mutation status (Cox PH coef. = −8.0 ± 3.4; P‐value = 1.5 × 10−2)." (PMID 34101353, 2021). "A forest plot of the combined CATNON, TCGA and TAVAREC survival data shows a summary estimate HR for non-R132H IDH1/2-mutated tumours of 0.56 with 95% CI [0.37, 0.85], association p = 0.006." (PMID 33740099, 2021). "ctDNA was detected in pre‐operative plasma samples of 31/83 (37%) patients whose tumour harboured an IDH1 or an IDH2 mutation." (PMID 34528398, 2021).
tumor (continued). "IDH1/2 mutations were significantly associated with an older age (p = 0.003), tumor origins (p < 0.001), tumor grades (p < 0.001), larger diameter (p = 0.003), relapse (p = 0.014), and patient mortality (p = 0.04)." (PMID 34085407, 2021). "Age of patients with wild-type IDH1 and EGFR increased with increase in tumour grade, while the age of patients with IDH1 or EGFR mutation remained constant." (PMID 34205437, 2021). "Compared with mutational profiling routinely analyzed using tumor samples, several additional targets with currently available therapies, including IDH1, IDH2, and PDGFRA mutations, were discovered." (PMID 33816227, 2021). "IDH1/2 mutations are causal for the disease and tumours often remain dependent on the mutation for growth." (PMID 33740099, 2021). "We demonstrate this interaction across multiple cell line models with engineered and endogenous IDH1/2 mutations, with robust anti-tumor activity in vitro and in vivo." (PMID 34027408, 2021). "It was reported that the tumor cells expressing mutations in IDH1/2 often appear distinct metabolic characteristics, especially the strong dependency on glutamine as the main cellular source of α-KG." (PMID 34425876, 2021). "In patients included in the CATNON randomised phase III clinical trial, those harbouring tumours with non-R132H IDH1/2-mutations indeed had longer overall survival compared to patients harbouring IDH1R132H mutated tumours." (PMID 33740099, 2021). "Whereas patients with IDH1 mutation concurrent with tumor-SVZ distance >10 mm exhibited particularly satisfactory prognosis and longer time to relapse." (PMID 34490090, 2021). "On the other hand, IDH1/2 mutations and D-2-HG exhibit anti-tumor effects through their metabolic impact." (PMID 34571995, 2021). "We built a Cox Proportional-Hazard model based on expression of genes common to the cilium biclusters and included known prognostic factors of patient age at diagnosis, tumor grade, and IDH1/2 mutated, 1p/19q co-deletion status." (PMID 34868236, 2021). "In short, mitosis is suppressed more in tumours with IDH1 mutation than in tumours with IDH1 wild-type." (PMID 34205437, 2021). "As expected, the non-R132H IDH1/2-mutated tumours cluster together at the high-methylation end of this spectrum." (PMID 33740099, 2021). "It has been suggested that Tau expression is epigenetically induced and regulates the tumor microenvironment in IDH1/2 mutated tumors, resulting in vascular normalization and limited tumor progression." (PMID 34830972, 2021). "Gender, age at surgery, extent of tumor resection, radiotherapy, chemotherapy, and IDH1 mutation status were used as variables." (PMID 33957923, 2021). "Compared with mutational profiling routinely analyzed using tumor samples, several additional genomic alterations with currently available therapies were discovered, including IDH1, IDH2, and PDGFRA mutations." (PMID 33816227, 2021). "Further analysis showed that a high-stage CRC tumor was significantly associated with a high IDH1 expression score (p = 0.0152)." (PMID 34234856, 2021). "Such non-R132H IDH1/2-mutated tumours also had a significantly lower proportion of tumours assigned to prognostically poor DNA-methylation classes (p < 0.001)." (PMID 33740099, 2021). "It therefore appears that tumor cells with IDH1 mutation display more sensitive to alkylating agents than wild-type cells due to the reduced repair kinetics and increased DNA damages." (PMID 34425876, 2021).